IL2 (interleukin 2)
Diseases named in the same sentence as IL2 in open-access papers (continued):
Sharing a sentence is not in itself a finding about the gene and the disease.
bacterial infection (49 papers, 2013 to 2025). "It has been shown that T cells in SLE patients have a reduced ability to produce IL-2 in response to antigenic stimuli, leading to their susceptibility to viral and bacterial infections." (PMID 37600067, 2023). "IL-2, IL-6, and IL-17 are systemic pro-inflammatory cytokines, and IL-10 is an anti-inflammatory cytokine, the concentration of which increases in acute inflammatory processes and exacerbations of chronic diseases caused by a viral or bacterial infection." (PMID 39937802, 2025). "The dysregulation of the cytokine profile upon contact with untreated Ti6Al4V-ELI discs, namely upregulation of IL-2 could be responsible for the decrease in Th17 frequency, and thus might contribute to implant-associated bacterial infection." (PMID 39439551, 2024). "Polyfunctional cytokine profiles (e.g., IFN-γ, TNF, IL-2) are frequently associated with improved outcomes in TB and other bacterial disease models, though to date, a profile that definitively correlates with protection against Mtb is lacking (for review see Lewinsohn, 201767)." (PMID 37898618, 2023). "Interleukin-2 may also disturb and impair neutrophil function, which may increase the risk of bacterial infection." (PMID 26557408, 2015). "DHEA boosts immunity by increasing interleukin-2 (IL-2) synthesis, increasing T-cell numbers, decreasing the release of inflammatory cytokines, and improving host resistance to viral and bacterial infections." (PMID 40821841, 2025). "Meanwhile, cytokine genes such as IL2, IL10, and IL15, associated with innate immunity against bacterial infection, mostly showed positive correlations in the GI immune-related tissues of infected animals." (PMID 38563680, 2024). "Compared to SARS-P, and in line with results obtained for IL-2 and IFNy, both cohorts with bacterial infection displayed significantly lower TNF levels on all three days." (PMID 36109525, 2022). "There is increasing evidence supporting sex dimorphism in the cytokine response to certain bacterial infections, such as an overproduction of IL-2 in males." (PMID 32373108, 2020). "IL-2, IL-10, and tumor necrosis factor (TNF) alpha showed weak diagnostic performance in distinguishing between bacterial and non-bacterial infections." (PMID 27486746, 2016). "IL-2 is also expressed during bacterial infection and has been suggested as a potential therapeutic target against Mycobacterium tuberculosis (TB) infections." (PMID 24086587, 2013). "As IL-10 is a cytokine that inhibits inflammation and promotes the production of anti-inflammatory cytokines such as IL-2 and TNF-α, these results suggest that B102 and B116 may help reduce inflammation caused by bacterial infections in the gut." (PMID 41114506, 2025). "As a consequence, T cells undergoing IL-2-driven strong LIP showed a full capacity to differentiate into functional effector and memory cells that can provide a protective response against pathogenic bacterial infection." (PMID 30190718, 2018). "Approaches to enhance host immunity and for reducing bacterial infection such as adenoviral gene therapy for over production of IL-2, using TNF-α pro-inflammatory cytokine and cyclic di-GMP have shown promise in boosting immunity and reduced bacterial infections." (PMID 28979250, 2017). "Similarly, during bacterial infection, CaMKKβ inhibition impaired the expansion of lymphocytes and T cells, reduced the proportion of T cells producing IL-2 or expressing CD122, and exacerbated A. hydrophila-induced T-cell apoptosis." (PMID 41249580, 2025). "Thus, the persistent elevation of IL-2 serum levels may indicate activation of adaptive immunity in spite of lymphocytopenia, which frequently accompanies bacterial infections." (PMID 23690657, 2013). "In our study, compared with healthy pregnant women, we observed a significant increase in IL‐2, IL‐6, IL‐10 and IFN‐γ in pregnant women with both influenza A and bacterial infection but lower levels of TNF‐α in both groups." (PMID 37638092, 2023).
bacterial infection (continued). "uPAR expression is upregulated on endothelial and hematopoietic cells during bacterial infection and in response to pro-inflammatory cytokines [e.g., tumor necrosis factor alpha (TNF-α), interferon gamma (IFN-γ), and interleukin 2 (IL-2)]." (PMID 35757694, 2022). "Th1 cells primarily mediate cellular immunity and control bacterial infection by secreting IFN-γ and IL-2 that function to destroy bacterial infection, particularly regarding intracellular bacteria such as Brucella species in macrophages." (PMID 35659087, 2022). "Classical type 1 cytokines and chemokines (e.g., IL-2, IL-12, IFN-γ, TNF-α, MCP-1/CCL2, MIP-1α/CCL3, and RANTES/CCL5) were predominantly induced around the peak of bacterial infection, and then decreased as bacterial replication was controlled at 28 dpi." (PMID 27479584, 2016). "Apart from IFN-γ, IL-4 and IL-10, there are several cytokines, such as IL-12, IL-2, IL-1, IL-18 and TNF-α that are involved in the regulation of immune responses to bacterial infections." (PMID 26619346, 2015). "Cytokines such as IL‐1β, IL‐2, IL‐5, IL‐6, IL‐8, IL‐12p70, IL‐17, and TNF‐α may be involved in the progression of COVID‐19 combined with bacterial infection." (PMID 39692539, 2024). "Upon bacterial infection, antigen‐presenting cells (i.e., IgM+ B cells and macrophages) provide the first and secondary signals for T cells, initiating the Ca2+‐NFAT, MAPK/ERK, NF‐κB, and mTORC1 pathways, leading to IL‐2 transcription and T cell activation." (PMID 36890649, 2023). "Moreover, low-dose IL-2 treatment in SLE patients has been previously shown to lead to a threefold reduction in the incidence of both viral and bacterial infection, potentially reflecting the prolonged heightened anti-inflammatory state in these patients." (PMID 37700317, 2023). "Some of their notable functions include:Cytokine production: During intracellular bacterial infection, γδΤ cells have the ability to produce interferon-gamma (IFN-γ) and interleukin 2 (IL-2), exhibiting Th1-like effects similar to helper T lymphocyte type 1 cells." (PMID 37597083, 2023). "When bacterial infections occur, the circulation levels of PCT increase, mainly due to the presence of bacterial endotoxins and exotoxins, as well as inflammatory cytokines, such as TNF, IL-2, and IL-6." (PMID 36553115, 2022). "Given the better understanding of the role of non-CD4+ immune cells in early control of severe bacterial infections, including Mtb and non-typhoidal Salmonella, we assessed beneficial effects of boosting these cell types with IL-2/anti-IL-2 complexes." (PMID 27391012, 2016). "In the presence of bacterial infection for example, inflammation is normally triggered, and the subsequent release of MIF allows for prolonged inflammation through the release of other pro-inflammatory cytokines like TNF-α, IL-1β, IL-6, IL-8, IL-2, and IFN-γ." (PMID 26741693, 2016). "In addition, IL-2 and IFN-γ, the necessary inflammatory regulators, belongs to Th1 cytokines, which can enhance the cellular immune function, mediate the cellular immune response, and play an active role in antiviral and bacterial infection." (PMID 32295580, 2020). "Serum cytokines including IL‐1β, IL‐2, IL‐5, IL‐6, IL‐8, IL‐12 p70, IL‐17, and TNF‐α were significantly higher in COVID‐19 patients with bacterial coinfections than those without bacterial infection." (PMID 39692539, 2024). "Thus, IL-2c (IL-2 bound by S4B6) expands effector cells (CD8 and CD4 T cells and NK-cells), and can lower pathogen burden in bacterial infections without signs of VLS." (PMID 30379932, 2018).
infectious disease (44 papers, 2010 to 2025). A disorder directly resulting from the presence and activity of a microbial, viral, or parasitic agent in humans. "Multifunctional T cells expressing a variety of cytokines (IFN-γ, TNF-α, IL-17, and IL-2) are associated with host protection against infectious diseases." (PMID 38932351, 2024). "CISH is involved in the IL-2 signaling pathway, and it is reportedly associated with infectious diseases." (PMID 35453806, 2022). "Indeed, IL-2, like IL-1, is a key mediator of the thermal-regulatory signaling activated by bacterial endotoxins and causing fever in patients with infectious diseases." (PMID 26495849, 2015). "Recent research on immune responses to infectious disorders has uncovered and characterized a vital function for multifunctional T cells that co-express IL-2, TNF-α, and IFN-γ." (PMID 36960295, 2023). "While co-production of IFN-γ, TNF-α and IL-2 by T cells is frequently investigated, reports on these cytokines in combination with IL-17A in the context of infectious diseases are rather scarce." (PMID 33584671, 2020). "As an important mediator in inflammatory and immune response of several infectious diseases, IL-2 is able to enhance host immunity and inhibit growth of tumors and parasites." (PMID 29785189, 2018). "It has been proposed that polyfunctional T cells, particularly those producing IFN-γ, TNF-α, and IL-2, correlate with protection and control of infectious diseases." (PMID 23762485, 2013). "Competition for IL-2 between effector and regulatory T cells has been suggested to control tolerance and immunity or the outcome of infectious disease." (PMID 23696736, 2013). "Children at risk for TB infection prospectively enrolled in our infectious disease unit were evaluated by in-house IFN-γ and IL-2 based ELISPOT assays using a panel of Mycobacterium tuberculosis antigens." (PMID 23029377, 2012). "IFN-γ has often been used as a single readout for Th1 responses, but recent studies of other infectious diseases have emphasized the importance of polyfunctional T cells co-producing IL-2, IFN-γ and TNF-α." (PMID 20505822, 2010). "Furthermore, they are also involved in immune response pathways (IL-5, IL-3, IL-2 signaling pathways, and B cell receptor signaling) and in controlling G1/S cell cycle, DNA damage response, and infectious diseases." (PMID 40287690, 2025). "In addition, by enhancing local immune responses and improving therapeutic outcomes, IL-2 is expected to contribute to the development of vaccines and the treatment of infectious diseases." (PMID 41376630, 2025). "Determining the fine kinetics of PP reconstitution after IL-2-induced B contraction could provide insight into mechanisms regulating PP dynamics in infectious versus non-infectious disease states." (PMID 32728053, 2020). "Activation of CD25 on mouse granuloma macrophages demonstrated an increased responsiveness of the macrophages to the powerful immunoregulatory lymphokine IL-2, which stimulates macrophages and other cells of the immune system for the treatment of infectious diseases." (PMID 27066505, 2016). "Also CD4 cells that co-express IFN-γ and IL-2 were measured using an IFN-γ /IL2 double color assay, because these cells, a subset of TH1 cells, have been associated with protection in several infectious diseases." (PMID 26258786, 2015). "Chicken IL-2 (ChIL-2) may enhance immunity against avian pathogens, which would introduce a new weapon for the control of infectious diseases in poultry." (PMID 19307173, 2011). "IFN-γ, TNF, and IL-2 are analyzed most often to assess cellular immunity to infectious diseases." (PMID 20520820, 2010). "In addition, mTOR inhibition in combination with the modulation of environmental cues using agents such as IL-2 might lead to new strategies for the treatment of infectious diseases or immunosuppressive tumors." (PMID 30619313, 2018).
infectious disease (continued). "The selective IL-2 stimulation of NK cells reduced viral loads and could overcome suppressive Treg activity suggesting that this might be an interesting new approach for the treatment of infectious diseases." (PMID 26220086, 2015). "IL-2 is an important immunomodulatory cytokine that is produced by multiple cell types including activated T-cells, dendritic cells, and NK cells and is crucial both for the immune responses against many infectious diseases and for the maintenance of tolerance." (PMID 24327799, 2013). "Beyond CD, the IL‐2 WBA shows promise as a versatile research and clinical tool across autoimmune, allergic, malignant, and infectious diseases where circulating antigen‐specific T cells are often present at low frequencies." (PMID 41395355, 2025). "Reactive oxygen species (ROS), IL-2, and IFN-γ are representative proinflammatory factors in many infectious diseases." (PMID 34200327, 2021). "Most diagnostic biomarkers consist of proteins, which are elevated not only in AR, but also during inflammation and infectious diseases, thus greatly lacking in specificity (e.g., IL-2)." (PMID 31031758, 2019). "In summary, our results suggest that the co-expressed pig IL-2 and FBC can provide potent antibacterial defense against microbial infection, which can be developed into a safe and effective immunopotentiator for the prevention of infectious diseases in the antibiotic-resistance era." (PMID 36290395, 2022). "White blood cells, lymphocytes and elevated levels of IL-2, IL-4, and IL-6 were also noticed in the mice in CpG-CNP group, indicating that CpG-CNP can serve as an effective adjuvant in order to improve the immune protection and resistance of porcine against infectious diseases." (PMID 32316990, 2020). "Based on these observations, albeit in the preclinical infectious disease setting, and those from the PIVOT IO 001 study, it is plausible that IL-2 receptor alpha-blocking strategies may inadvertently abrogate the otherwise synergistic effects of combining anti-PD-1 with wild-type IL-2." (PMID 39025948, 2024). "IL-2 has been recently linked to improved secondary proliferation, while the role of IL-7 in maintenance of CD4+ memory cells has been demonstrated in homeostatic proliferation, but its role in protective memory populations in infectious disease protective has not been fully investigated." (PMID 22039531, 2011).
inflammation (35 papers, 2009 to 2025). Aberrant reaction of the microcirculation characterized by movement of fluid and leukocytes from the blood into extravascular tissues. "FB1, as a toxic stimulate factor, can trigger abnormal expression of TNF-α and inflammatory factors, including IL-1β (Interleukin-1 bata), IL-2 (Interleukin-2), IL-4 (Interleukin-4), and IL-10 (Interleukin-10), and cause intestinal inflammation in mice." (PMID 38769285, 2024). "Overall, we identify that duplication of the IL2RA locus can associate with VEO-IBD and suggest that increased IL-2 signaling predisposes to colonic intestinal inflammation." (PMID 34226674, 2021). "On the other hand, IL-2 is associated with skin and lung inflammation and has anti-inflammatory effect." (PMID 30925685, 2019). "IL-2 deletion in CD11chighMHCII+ DCs caused more severe, spontaneous intestinal inflammation in Il2CD11c mice compared to Cnb1CD11c mice, which was characterized by expansion of activated CD4+ effector T cells and substantial reduction of Treg cells." (PMID 29549257, 2018). "The data above suggested that IL-2 deficiency, either locally or systemically, might contribute to renal inflammation in (NZB × NZW) F1 mice." (PMID 31614462, 2019). "However, high expression of the IL-2 signaling pathway could predispose to colonic intestinal inflammation." (PMID 36084127, 2022). "Studies found that altered flora in patients with neonatal necrotizing small bowel colitis led to significant intestinal inflammation, resulting in increased expression of IL‐1, IL‐2, IL‐4, IL‐6, IL‐8, IL‐10, TNF‐α, IFN‐γ, and IL‐17 in samples." (PMID 40119640, 2025). "During an inflammatory response, IL-2 exhibits various and often opposing functions; thus, it has a highly complex role in the pathogenesis of systemic inflammation and inflammatory diseases more broadly." (PMID 39766252, 2024). "This comparison suggests that the skin and lung inflammation in Sf mice also involves Th1 responses and that a critical step shared by both Th1 and Th2 responses for skin and lung inflammation must have been inhibited in Sf.Il2−/− mice." (PMID 24832045, 2012). "Our studies suggest that the most influential cytokine for skin and lung inflammation correlates with serum IL-2." (PMID 24832045, 2012). "As for airway inflammation, combined use of IL-2 and dexamethasone could significantly reduced bronchial inflammation and mucus production, which were verified by investigator-independent computer-based analysis of H&E or PAS-stained lung sections." (PMID 27527926, 2016). "Treatment with acetic acid resulted in severe histopathological destruction (necrosis, skin lesions, and inflammation) as well as an increase in the levels of the tongue tissue proinflammatory cytokines TNF-α and IL-2." (PMID 35161436, 2022). "Pro-inflammatory cytokines such as IL-1α, IL-1β, IL-2, IL-5, IL-6, IFN-γ, MCP-1, MIP-1α, MIP-1β and TNF-α are shown to play an essential role in inducing age-related chronic inflammation." (PMID 31181695, 2019). "Chronic inflammation is known to play a major role in the pathological mechanism of COPD, and inflammatory cytokines, such as MCP-1, IL-2, IL-6, and IL-10, are known to promote inflammation." (PMID 29234369, 2017). "Because IL-2 is needed for TRG of Th1 and Th2 cells, it has a more dominant role than Th2 IL-4 in regulating skin and lung inflammation in the Sf mice." (PMID 24832045, 2012). "Autopsy studies have shown that acute myocardial inflammation is common in the first 5 days following IL-2 therapy, being seen in up to 75% of patients regardless of symptoms or cause of death." (PMID 35741162, 2022). "Secondly, ILC3s can support Treg cell survival and/or expansion in the intestine through IL-2 to prevent chronic gut inflammation Notably, T cell-specific deletions of IL-2 do not affect Tregs in the small intestine." (PMID 35163778, 2022).
inflammation (continued). "Systemic inflammation in obese boys was characterized by higher expression of TNF-β (p = 0.011), IL-15 (p = 0.004), and IL-2 (p = 0.046) and significantly lower concentrations of anti-inflammatory cytokines such as IL-10 (p = 0.035) and IL-13 (p = 0.002), compared to eutrophic males." (PMID 33526854, 2021). "The phenotype of Il2−/− mice is dominant because Sf.Il2−/− mice failed to develop skin and lung inflammation whereas their liver inflammation remained." (PMID 24832045, 2012). "The results showed that CD4+ T-cells of Sf but not Sf.Il2−/− mice induced skin and lung inflammation and the extent of inflammation difference was highly significant." (PMID 24832045, 2012). "Recent data have suggested interferon-gamma (IFN-γ) and/or interleukin-2 (IL-2) to be protective rather than pro-inflammatory cytokines that could be involved in the down-regulation of RA-related chronic inflammation." (PMID 24221190, 2014). "Importantly, Il2-/- and Sf.Il2-/- mice do not display skin and lung inflammation associated with Sf mice, raising the possibility that CD103 controlled by IL-2 is important for skin and lung inflammation in Sf mice." (PMID 19272184, 2009).